POLE (DNA polymerase epsilon, catalytic subunit)
Description:
Catalytic component of the DNA polymerase epsilon complex. Participates in chromosomal DNA replication (By similarity). Required during synthesis of the leading DNA strands at the replication fork, binds at/or near replication origins and moves along DNA with the replication fork (By similarity). Has 3'-5' proofreading exonuclease activity that corrects errors arising during DNA replication (By similarity). Involved in DNA synthesis during DNA repair. Along with DNA polymerase POLD1 and DNA polymerase POLK, has a role in excision repair (NER) synthesis following UV irradiation.
Synonyms: POLE1; CRCS12; FILS; IMAGEI
Tractability: Small molecule: an approved drug acts on it; a structure with a bound ligand is known; it belongs to a druggable protein family. Antibody: its Gene Ontology location is reachable by antibodies, with high confidence; the Human Protein Atlas places it where antibodies can reach. PROTAC: ubiquitination databases record sites on it.
Gene: Protein-coding gene on chromosome 12 (132,623,753 to 132,687,376, reverse strand). Ensembl gene ENSG00000177084.
Subcellular location: Nucleus
Subcellular location (Human Protein Atlas): Nucleoplasm; Plasma membrane
Pathways (Reactome):
DNA Repair: Dual Incision in GG-NER; Dual incision in TC-NER; Gap-filling DNA repair synthesis and ligation in GG-NER; Gap-filling DNA repair synthesis and ligation in TC-NER; HDR through Homologous Recombination (HRR); PCNA-Dependent Long Patch Base Excision Repair; Recognition of DNA damage by PCNA-containing replication complex; Termination of translesion DNA synthesis
DNA Replication: Activation of the pre-replicative complex; DNA replication initiation
Gene Ontology:
Molecular function: chromatin binding; DNA binding; DNA-directed DNA polymerase activity; protein binding; DNA polymerase activity; single-stranded DNA 3'-5' DNA exonuclease activity; nucleic acid binding; nucleotide binding; zinc ion binding
Biological process: base-excision repair, gap-filling; DNA replication; DNA synthesis involved in DNA repair; DNA-templated DNA replication; G1/S transition of mitotic cell cycle; nucleotide-excision repair, DNA gap filling; DNA replication proofreading; leading strand elongation; DNA biosynthetic process; DNA repair; embryonic organ development
Cellular component: epsilon DNA polymerase complex; nucleoplasm; nucleus; plasma membrane
Genetic constraint (gnomAD): Loss-of-function variants: 181 observed, 273.08 expected, observed/expected ratio (o/e) 0.66, 90% interval 0.59 to 0.75. The upper end of that interval is the gene's LOEUF score, 0.75, which puts it in group 3 of 6, group 1 being the genes least tolerant of losing a copy. Missense variants: 2,657 observed, 3,061.6 expected, observed/expected ratio (o/e) 0.87, 90% interval 0.84 to 0.9. Synonymous variants: 1,201 observed, 1,195.3 expected, observed/expected ratio (o/e) 1, 90% interval 0.96 to 1.05.
Gene-disease validity (ClinGen):
ClinGen rates the evidence that POLE causes each of these diseases.
POLE-related polyposis and colorectal cancer syndrome (autosomal dominant): Definitive. An autosomal dominant hereditary syndrome caused by germline pathogenic POLE variants.
Cancer hallmarks: proliferative signalling (promotes); genome instability and mutations (suppresses); escaping immune response to cancer; change of cellular energetics
Homologues: Orthologues: chimpanzee POLE (99% identical), macaque POLE (98% identical), pig POLE (93% identical), guinea pig POLE (92% identical), dog POLE (91% identical), rat Pole (91% identical), mouse Pole (91% identical), rabbit POLE (90% identical), tropical clawed frog pole (81% identical), zebrafish pole (80% identical), Drosophila melanogaster PolE1 (55% identical), Caenorhabditis elegans pole-1 (44% identical).
Diseases named in the same sentence as POLE in open-access papers:
POLE is named in the same sentence as 177 diseases in open-access papers, as found by Europe PMC text mining. Sharing a sentence is not in itself a finding about the gene and the disease. The quoted sentences say what the papers report.
endometrial cancer (291 papers, 2014 to 2026). Primary or metastatic malignant neoplasm involving the endometrium (mucous membrane that lines the endometrial cavity). "Somatic POLE variants have been observed in 2%–8% of CRCs and 7%–15% of endometrial cancers; however, somatic POLD1 variants are extremely rare." (PMID 41214301, 2026). "This study developed and validated a Self-competitive Fishing (SCF) primer qPCR system as a rapid, cost-effective alternative to next-generation sequencing (NGS) for detecting POLE exonuclease domain mutations (EDMs) in endometrial cancer." (PMID 41899408, 2026). "POLD1- related cases are linked to endometrial cancer, breast cancer, and brain tumors, whereas POLE- related cases are associated with duodenal adenomas and cancer, ovarian cancer, brain tumors, pancreatic cancer, breast cancer, and melanoma." (PMID 41214301, 2026). "Sensitivity testing used POLE-mutated DNA diluted in wild-type DNA, while precision was confirmed by analyzing 86 endometrial cancer samples against NGS results." (PMID 41899408, 2026). "A systematic literature search was conducted to identify reports of recurrence, progression, or cancer-related death in POLE-mutated endometrial carcinoma, with extraction of recurrence patterns, genomic features, treatment, and outcomes." (PMID 42041738, 2026). "The “ultra-mutated” nature of POLE-mutant endometrial cancer displays a high mutational burden and improves responses to immunotherapy." (PMID 40761799, 2025). "Conversely, the risk of endometrial cancer by age 70 seems higher in POLD1 (75%) than in POLE (25%)." (PMID 41487566, 2025). "This reflects the known rarity of POLE exonuclease-domain mutations in endometrial cancer, typically reported in ~7–12% of cases in large sequencing cohorts such as TCGA." (PMID 41226475, 2025). "The molecular classification of endometrial cancer significantly affects a patient’s prognosis, especially in POLE mutation cases, which are typically associated with more favorable outcomes." (PMID 40761799, 2025). "POLE mutations, particularly within the exonuclease domain, are known to confer an ultramutated phenotype in endometrial cancer, characterized by exceptionally high tumor mutational burden and a favorable prognosis." (PMID 41226475, 2025). "Patients with endometrial cancer (EC) characterized by POLE hotspot mutations (POLEmut) have exceptional survival outcomes." (PMID 39865420, 2025). "This comprehensive genomic analysis of 596 patients with endometrial cancer investigated the characteristics of DNA polymerase epsilon (POLE) mutations." (PMID 39865420, 2025). "POLE-mutated tumors represent a unique molecular subgroup in endometrial cancer, often associated with improved outcomes, even among cases with poor differentiation." (PMID 40072110, 2025). "Future research should analyze more similar cases to elucidate the clinical characteristics, prognostic factors, and treatment responses associated with POLE mutations in endometrial cancers." (PMID 40761799, 2025).
endometrial cancer (continued). "The Cancer Genome Atlas (TCGA) established a molecular classification scheme to identify four subtypes of endometrial cancer (EC) based on genomic, transcriptomic, and proteomic features, one of which was a POLE-mutated subtype." (PMID 40310397, 2025). "POLE mutation status serves as an important biomarker for prognosis, guiding risk stratification, and treatment decisions in endometrial cancers." (PMID 40072110, 2025). "In light of these observations, the present study aimed to comprehensively characterize miRNA expression profiles in endometrial cancer, with a dual focus on their role in oncogenesis and their association with POLE mutation status." (PMID 41226475, 2025). "The presence of POLE mutation represents an independent favorable prognostic factor in patients with endometrial carcinoma." (PMID 41300972, 2025). "Despite this resistance to chemotherapy, POLE-mutated endometrial carcinomas are associated with a favorable prognosis." (PMID 40004914, 2025). "Some tumors, particularly colorectal and endometrial carcinomas, carry hot-spot alterations in POLE gene encoding for DNA polymerase; POLE-mutated malignancies usually have high TMB and are responsive to ICI." (PMID 40135049, 2025). "POLE mutations in endometrial carcinoma have a significant impact on treatment resistance, particularly in the context of platinum-based chemotherapy." (PMID 40004914, 2025). "POLE-mutated endometrial carcinomas have improved prognosis due to high TIL infiltration and immunogenicity, not chemotherapy sensitivity." (PMID 40264788, 2025). "Endometrial carcinomas with POLE mutations are associated with an excellent prognosis, particularly in Grade 3 endometrioid adenocarcinomas." (PMID 39923442, 2025). "Typically, POLE ultra-mutated endometrial cancers are found in younger women with earlier stage, but higher-grade tumors with significant lymphocytic infiltration." (PMID 38539507, 2024). "POLE mutations were observed in 4.9% of colorectal cancers (92/1,870), 6.9% of endometrial cancers (307/4,481), and 0.6% of ovarian cancers (48/8,190)." (PMID 38282550, 2024). "Overall, in endometrial cancer, 75% of the POLE variants occurred in POLE ExoD signature sequence contexts." (PMID 38282550, 2024). "We validated our findings by analyzing the sequencing data from TCGA, which included 46 tumors (78% endometrial cancer or colorectal cancer) with POLE variants (access date: February 2022)." (PMID 38282550, 2024). "Endometrial cancer patients with POLE mutations have a better prognosis, with significantly lower rates of recurrence and mortality compared to those with wild-type POLE." (PMID 39768855, 2024). "In high-grade endometrial cancer, patients with POLE mutations rarely experience recurrence, while the recurrence rate in wild-type POLE patients can be as high as 30.9%." (PMID 39768855, 2024).
endometrial cancer (continued). "A retrospective cohort study identified that women with POLE mutated endometrial cancer had excellent outcomes, suggesting that further research is required to determine if treatment is indicated in this group of women." (PMID 39219879, 2024). "It is important to note that POLE mutation is closely associated with a favorable prognosis for endometrial cancer patients." (PMID 38238314, 2024). "Based on comprehensive genomic analysis, TCGA identified four prognostic subtypes of endometrial cancer: DNA polymerase epsilon (POLE) ultra-mutated, microsatellite instability (MSI) hypermutated, copy-number low, and copy-number high." (PMID 38539507, 2024). "When segregating by cancer type, POLE variants in Group 4 were observed in colorectal cancer (n = 21), endometrial cancer (n = 118), and in ovarian cancer (n = 4)." (PMID 38282550, 2024). "In research on endometrial cancer, POLE mutations account for 7% to 12% of all gene mutations in endometrial cancer." (PMID 39768855, 2024). "Overall, approximately 8–10% of all endometrial cancers have POLE mutation, especially in young women with high-grade and early disease." (PMID 39062983, 2024). "Somatic POLE mutations affecting proofreading are relatively rare, typically observed in approximately 2%–8% of colorectal cancers and approximately 7%–15% of endometrial cancers, and less commonly in other tumors." (PMID 38282550, 2024). "POLE-mutation-associated endometrial cancers are usually high-grade tumors with deep myometrial and lymphovascular invasion, and tend to have a good prognosis." (PMID 39061183, 2024). "Mutations within the POLE exonuclease region have been associated with improved survival in endometrial cancer patients receiving immune checkpoint inhibitor treatment and have been identified as valuable prognostic factors." (PMID 38238314, 2024). "The somatic copy number alteration (SCNA) module further demonstrated a positive association between immune infiltration levels and POLE mutations in endometrial cancer." (PMID 38238314, 2024). "POLE driver mutations in the exonuclease domain (ExoD driver) are prevalent in several cancers, including colorectal cancer and endometrial cancer, leading to dramatically ultra-high tumor mutation burden (TMB)." (PMID 38282550, 2024). "Collectively, these findings suggest that POLE has a high mutation frequency in endometrial cancer, and its mutations positively correlate with immune infiltration levels." (PMID 38238314, 2024). "The TCGA Research Network reported that the POLE-mutated subtype was identified in 7% of all endometrial cancers." (PMID 39734232, 2024). "To investigate the pathological significance of POLE mutations in endometrial carcinogenesis, we analyzed the POLE expression profile in various endometrial cancer datasets via the cBioPortal Cancer Genomics database." (PMID 38238314, 2024). "Further research has provided guidance on the classification of POLE-mutated endometrial cancer, thus facilitating its use in clinical practice." (PMID 39219879, 2024). "Analysis of the TCGA endometrial carcinoma cohort using only ECs with a known pathogenic hotspot POLE-EDM as a “truth set” allowed the development of a scoring system, with well-defined cutoff points for examining pathogenicity of POLE variants." (PMID 39239272, 2024). "We collected 596 endometrial carcinoma specimens from patients visiting our hospital, among which approximately 13.14% were found to harbor POLE mutations." (PMID 38238314, 2024).
endometrial cancer (continued). "Incorrect annotation of a POLE variant can lead to erroneous classification of an endometrial carcinoma within the POLE-mutated subgroup, and this can impact the clinical management of the patient." (PMID 39239272, 2024). "This subtype is characterized by high mutational rates (above 100 mutations per megabase) attributed to POLE mutations, and it has a high rate of 5-year recurrence-free survival rate for patients with grade 3 early endometrial carcinomas, above 96%." (PMID 39062983, 2024). "Through bioinformatics analysis of sequencing data, we identified 157 distinct POLE mutations from the 596 endometrial carcinoma specimens." (PMID 38238314, 2024). "The ESGO/ESTRO/ESP guideline recommends considering the omission of adjuvant treatment for patients with endometrial carcinoma stage I, II, and pathogenic POLE mutation." (PMID 39062983, 2024). "Among these subtypes, new hotspot mutations in the exonuclease domain of POLE defined a subgroup of endometrial cancers with ultrahigh somatic mutation frequencies, high tumor infiltrated lymphocytes and favorable outcomes." (PMID 36765365, 2023). "Somatic POLE exonuclease domain mutations (EDMs) have been reported in 7–12% endometrial cancers (ECs) and 1–2% CRC." (PMID 36765365, 2023). "In order to assess the prevalence of the NSMP and POLE-mt signatures, future prospective studies assessing mutations in the exonuclease domain of Polymerase-ε on all endometrial cancers samples are necessary." (PMID 37958382, 2023). "KEYNOTE-028, a multicohort phase Ib clinical study, enrolled 24 patients with PD-L1-positive advanced endometrial cancer with one patient distinguished by POLE mutation, one MSI, and the other patients undefined, all receiving pembrolizumab treatment." (PMID 37109350, 2023). "POLE- mutation endometrial cancer with a good prognosis demonstrates great sensitivity to immunotherapy with strong efficacy generated by monotherapy, but it only accounts for a small percentage of endometrial cancer and rarely recurs." (PMID 37109350, 2023). "Twelve pMMR cases showed low TMB and MSS/MSI-L, and the remaining one pMMR/MSS case of endometrial cancer which had a POLE mutation displayed high TMB." (PMID 37953261, 2023). "Significantly, all ECCC cases with POLE mutations have shown prognoses similar to other POLEmut endometrial cancers." (PMID 37627129, 2023). "The additional cases that were found were associated with colorectal and endometrial cancers, which are disease-specific for POLE/POLD1 exonuclease deficiency associated tumors." (PMID 38067377, 2023). "It identified four subgroups of endometrial cancer with different molecular profiles: tumors with mutated DNA polymerase ε (POLE), tumors exhibiting microsatellite instability (MSI), and tumors with copy-number low (CNL) and copy number high (CNH)." (PMID 38201606, 2023). "In 2013, TCGA devised a new classification schema for endometrial cancer with the identification of four molecular subtypes: POLE ultra-mutated, microsatellite instability hypermutated, copy-number low, and copy-number high." (PMID 37568665, 2023). "In endometrial cancer, all eight (1.4%) POLE exonuclease-mutated tumors were TMB-H (median TMB, 90.78 mut/Mb), of which only one was MSI-H." (PMID 38201563, 2023). "In the public TCGA study, endometrial cancer was divided into four subtypes, namely, POLE hyper-mutation, high mutation microsatellite instability (MSI), and non-specific molecular variation (NSMP)." (PMID 36726804, 2023).